SIRT6 (sirtuin 6)
Diseases named in the same sentence as SIRT6 in open-access papers (continued):
Sharing a sentence is not in itself a finding about the gene and the disease.
cancer (continued). "SIRT6 has emerged as an important target for cancer prevention and treatment." (PMID 32488123, 2020). "These controversial reports on the role of SIRT6 in cancer growth suggest that the effect of SIRT6 expression might differ according to the condition of the cancer itself or the cancer-associated environment." (PMID 33198792, 2020). "The prognostic significance of SIRT6 expression might be related to the role of SIRT6 on the proliferation of cancer cells, and SIRT6 is known as an important regulator of cellular proliferation." (PMID 33198792, 2020). "Furthermore, our results show that suppression of SIRT6 or inhibition of the SIRT6-mediated DNA damage repair pathway synergizes with the anti-cancer effect of doxorubicin." (PMID 33198792, 2020). "Furthermore, SIRT6 affected cancer cell proliferation by suppressing the transcriptional activity of c-Myc." (PMID 33335996, 2020). "Several SIRT6 inhibitors have been reported 62-67, and they exhibit potential for the treatment of certain cancers in which elevated SIRT6 expression may lead to malignancy 16-20." (PMID 32483423, 2020). "However, few studies have focused on SIRT6-induced autophagy in cancer, particularly in thyroid cancer." (PMID 32983963, 2020). "These controversial reports on the role of SIRT6 in human cancers suggest that the impact of SIRT6 expression in cancer patients might differ depending on cancer type and/or characteristics of cancer patients included in the study." (PMID 33198792, 2020). "Inhibition of SIRT6 also sensitizes cancer cells to chemotherapy." (PMID 32392755, 2020). "Therefore, further study is needed to clarify the various roles of SIRT6 in tumorigenesis and cancer progression." (PMID 33198792, 2020). "Taken together, Galloflavin and Ellagic acid targeting SIRT6 activity may provide a new insight in the development of anti-cancer therapy." (PMID 32905943, 2020). "In line with biological effects regulated by SIRT6, the SIRT6 inhibitors we identified also increased glucose uptake by muscle cells and potentiated the anticancer effects of other chemotherapeutic drugs in cancer cells." (PMID 32736564, 2020). "Taken together, compounds targeting SIRT6 activity may provide a new approach in the development of anti-cancer therapy." (PMID 32905943, 2020). "As a result, inhibition of SIRT6 may be useful against cancer-induced inflammation, angiogenesis and metastasis." (PMID 31591350, 2019). "SIRT6, another member of the sirtuin protein family, functions in multiple complex ways in cancer." (PMID 31817470, 2019). "In this regard, we note that SIRT6 inhibitors are under development as anti-cancer drugs." (PMID 30886604, 2019). "Because sirtuin family members, play an important role in metabolic regulation of cancer cells, especially SIRT6, specific inhibitors may provide an additional strategy to target cancer cell metabolism." (PMID 30356832, 2018). "In agreement with our results, SIRT6 is involved in EMT of various human malignant tumors." (PMID 30524965, 2018). "Therefore, further study is needed to clarify the role of SIRT6 in cancer progression and the treatment of cancer." (PMID 30524965, 2018). "Even though further studies may be warranted in this case, this pivotal knowledge about SIRT6 up-regulation may prove to be very useful when combating tumorigenesis in the liver or premalignant liver lesions at the early stages of cancer development." (PMID 29966233, 2018). "In addition, SIRT6 expression is higher in cancer tissue compared with normal tissue in esophagus, thyroid, and melanocytes." (PMID 30524965, 2018). "The study of SIRT6 in relation to cancer raises more questions than actual answers." (PMID 29966233, 2018).
cancer (continued). "Therefore, compounds that can regulate SIRT6 activities are considered as promising therapeutics for age-related diseases including cancer, diabetes, neurodegenerative diseases and metabolic disorders." (PMID 29515203, 2018). "Especially, although we did not perform such a test, a pre-clinical in vivo experiment might be helpful in understanding the role of SIRT6 in cancer progression." (PMID 30524965, 2018). "In cancer, the role of SIRT6 in autophagic processes has been poorly investigated." (PMID 30250025, 2018). "In this contest, exploiting the possibility to act on the autophagic process, through a direct modulation of SIRT6, could be of fundamental importance representing a novel avenue in cancer therapy." (PMID 30250025, 2018). "However, there are controversial reports regarding the prognostic significance of SIRT6 expression in human cancers." (PMID 30524965, 2018). "Therefore, further study is needed to clarify the prognostic role of SIRT6 expression in human cancers." (PMID 30524965, 2018). "However, COX-2 also suppresses skin tumorigenesis and their relationship with SIRT6, making it an interesting target for the discovery of drugs with anti-inflammatory and anti-cancer properties." (PMID 29556059, 2018). "This, is conjunction with its linked roles in metabolism, heart disease, genetic stability, and cancer may make SIRT6 a crucial player in human aging." (PMID 29966233, 2018). "Therefore, a careful approach and further study is needed to explore the role of SIRT6 in human cancers." (PMID 30524965, 2018). "Additionally, we observed that in an in vivo model of cancer cachexia, Mstn expression coupled with downregulation of SIRT6." (PMID 28928419, 2017). "Thus, the role of SIRT6 in cancer appears to be quite complex and possibly context-and tissue-specific." (PMID 29234488, 2017). "SIRT6 is involved in multiple cellular processes including transcription, genome instability, telomere integrity, DNA repair, inflammation, metabolism and ageing, and cancer." (PMID 29100306, 2017). "SIRT6 activity affects the development of several cancer subtypes, but it is still unclear whether it is a tumor suppressor or promoter, or both." (PMID 28635654, 2017). "Sirt6 is a sirtuin family member that participates in the control of a wide range of pathophysiological processes, including glucose homeostasis, cardiovascular diseases, cancer and longevity." (PMID 29371988, 2017). "Decreased SIRT6 expression level is found in several human cancers." (PMID 28406396, 2017). "Also, the effect of SIRT6 on cancer suggests a SIRT6-based treatment is viable for at least some specific types of cancer." (PMID 27659520, 2017). "SIRT6 is a tumor suppressor protein that has been studied in many different types of cancer." (PMID 28406396, 2017). "For instance, given that the cell lines used U937 and HeLa cells are in vitro models of cancer, possible regulation of NFAT5 by SIRT6, may translate into discovery of other novel regulatory steps leading to cancer." (PMID 27536992, 2016). "Sirtuin6 (SIRT6), a member of the sirtuins protein family, plays multiple complex roles in cancer." (PMID 27777384, 2016). "This is suggestive of particular cancer cell-type specific activities of SIRT6." (PMID 25907989, 2015). "We hypothesize that the oncogenic role of E2F1 can also be attributed to its promotion of glycolysis through suppressing SIRT6 expression and activity in cancer cells." (PMID 25816777, 2015). "SIRT6 itself is also subject to post-translational regulation in cancers." (PMID 25085992, 2014). "Activation of SIRT6 in preformed cancers might conceivably represent a strategy to inhibit signaling through these oncogenic transcription factors." (PMID 25085992, 2014).
cancer (continued). "While previous studies have demonstrated that SIRT6 influences mitochondrial function through the regulation of aging-related signaling pathways, the specific role of SIRT6 in mitochondrial function regulation and its impact on tumorigenesis remain underexplored in cancer models." (PMID 41362737, 2026). "Targeting SIRT6 therapeutically could offer novel avenues for cancer treatment, with the potential to modulate its activity through small molecules or gene therapy, offering hope for personalized cancer therapies." (PMID 41463311, 2025). "Notably, rare SIRT6 variants found in centenarians exhibit stronger suppression of LINE-1 retrotransposons, enhanced genomic stability, and are more effective than wild-type SIRT6 in inducing apoptosis in cancer cells." (PMID 41244840, 2025). "Our findings show that SIRT6 overexpression attenuates, but SIRT6 knockout exacerbates, adipocyte lipolysis induced by LLC cell‐conditioned medium in cell, further validating the beneficial effects of SIRT6 against lipolysis in cancer cachexia‐associated adipocytes." (PMID 39971710, 2025). "Furthermore, we found that BLA could deacetylate two histones, H3K9Ac and H3K56Ac, by upregulating the expression of SIRT6, thus inhibiting cancer progression." (PMID 39845013, 2025). "Moreover, using a phosphoproteomics approach, we previously assessed the enzymatic activity of three enzymes associated with cancer and only present in sEVs derived from the cancerous cell lines MCF7 and MDA-MB-231: ATP citrate lyase (ACLY), sirtuin-1 (SIRT1) and sirtuin-6 (SIRT6)." (PMID 37189694, 2023). "SIRT6 is overexpressed in various types of cancer and its inhibition may have anti-cancer effects." (PMID 38203666, 2023). "UBCS039 induced cell death and reduced cell proliferation in cancer cell lines of different origin, including non-small cell lung, colon and epithelial cervix carcinoma, and fibrosarcoma, clearly demonstrating that pharmacological SIRT-6 activation triggers an autophagy-related cell death." (PMID 36080416, 2022). "Therefore, SIRT7 and SIRT1/SIRT6 play opposite roles in the metabolism, inflammation, and cancer." (PMID 36012298, 2022). "SIRT6 has emerged as a critical player in the onset and progression of many human diseases, including lifespan regulation, cardiovascular diseases, neurodegenerative diseases, viral infections, cancer, diabetes, and inflammation, functioning via its enzymatic activity." (PMID 36117172, 2022). "In the pathway of central carbon metabolism in cancer, SIRT6 could directly inhibit hypoxia-inducible factor 1α (HIF-1α), and SIRT3 could inhibit HIF-1α by repressing HIF-1 signaling, which then affected metabolic process such as glycolysis and tricarboxylic acid (TCA) cycle." (PMID 35136826, 2022). "However, when considering the controversial reports on the effects of SIRT6 in cancer cells, the elevated expression of SIRT6 might not be sufficient to predict SIRT6 activity in human cancers." (PMID 34359939, 2021). "However, in certain types of cancer, SIRT6 is classified as a tumor suppressor." (PMID 34639169, 2021). "The involvement of SIRT6 in these key processes may explainits dual role in cancer." (PMID 34213345, 2021). "SIRT6 is a multifunctional nuclear protein, involved in different physiological processes and pathological conditions, such as genome stability, longevity, glucose metabolism, neurodegenerative, heart and liver diseases, diabetes, inflammation, cancer, and bone disorders." (PMID 33482921, 2021). "Indeed, inhibitors may target different SIRT6-mediated pathways contributing to cancer progression such as DNA repair mechanisms, cell differentiation and inflammatory response." (PMID 33800266, 2021).
cancer (continued). "Together, our findings uncover a role of SIRT6 in suppressing malignant cancer cell properties and reveal a novel mechanism through which SIRT6 may interface with histone acetylation machinery to reinforce and fine tune its effects on histone acetylation dynamics in cancer cell gene regulation." (PMID 34573442, 2021). "Thus, the relationship between SIRT6 and cancer development remains to be elucidated." (PMID 34244565, 2021). "However, there came different opinions on the role of SIRT6 in apoptosis of cancer cells." (PMID 34927546, 2021). "In this study, we show that SIRT6 deficiency increases the nuclear ACLY protein, nuclear acetyl-CoA abundance, and locus-specific histone acetylation, which in turn drive an up-regulation of PDGFRA and other genes that contribute to invasive cancer cell adhesion and migration phenotypes." (PMID 34573442, 2021). "Although the exact role(s) of NMNAT2 have yet to be fully elucidated, there is considerable evidence that it may promote cancer cell survival by accelerating glycolysis via a mechanism that includes a reduction in the expression of the transcriptional regulator sirtuin SIRT6." (PMID 33711921, 2021). "Therefore, the relationship between CSNK2A1 and SIRT6 phosphorylation on Ser338 might be important in cancer therapy with regards to overcoming resistance to anti-cancer therapeutics." (PMID 34359939, 2021). "Therefore, depending on the specific type of cancer, SIRT6 activation or inhibition may be beneficial." (PMID 33800266, 2021). "However, the mechanism through which SIRT6 controls cancer progression is intriguing and, depending on the biologic context, both increased and reduced SIRT6 activity could be exploitable by cancer cells." (PMID 32488123, 2020). "However, the role depends on the type of cancer since SIRT6 can also promote tumorigenesis." (PMID 32905943, 2020). "However, when considering the role of SIRT6 in the repair of DNA damage, SIRT6 might be involved in the effectiveness of anti-cancer treatment." (PMID 33198792, 2020). "Therefore, this new quinazolinedione-based SIRT6 inhibitors could potentially find therapeutic applications as adjuvants in cancer treatment." (PMID 31591350, 2019). "Therefore, SIRT6 inhibitor may serve as a potential therapeutic agent in diabetes, immune-mediated disorders, and cancer." (PMID 31708789, 2019). "Therefore, further study is needed to clarify the exact role of SIRT6 in cancer invasiveness." (PMID 30524965, 2018). "However, an oncogenic role of SIRT6 also has been reported in various human cancers." (PMID 30524965, 2018). "However, SIRT6 activity can also promote apoptosis in non-cancer cells, including neurons." (PMID 30409187, 2018). "However, the exact role of SIRT6 in cancer is still not well understood." (PMID 28406396, 2017). "SIRT6 augmentation in cancer cells, but not in normal cells, causes massive apoptosis." (PMID 28928419, 2017). "Accordingly, overexpression of SIRT6 in different cancer cell lines reduces cell proliferation and induces apoptosis Although some of these effects seem to be mediated by its deacetylase activity, SIRT6’s MARylation activity might as well be responsible for apoptosis induction." (PMID 26426055, 2015). "Sirtuin 6 (SIRT6), a member of the NAD+-dependent Sirtuin protein deacetylase family, plays a pivotal role in aging, cancer, inflammation, and cardiovascular diseases." (PMID 39819383, 2025). "Other sirtuin isoforms, such as SIRT1, play contrasting roles to SIRT6 because SIRT1 prevents muscle wasting in response to GC and cancer." (PMID 40806744, 2025).
cancer (continued). "Overall, these findings show that there are many ways NK cell activity is reduced in cancer, influenced by epigenetic enzymes like SIRTs (SIRT1, SIRT2, SIRT6), surface regulators like CD38, and signaling pathways like TGFβ-SMAD4." (PMID 41425553, 2025). "In PDAC, SIRT6 knockdown led to increased acetylation of H3K9 and H3K56 at the promoters of oncogenes Lin28b and c‐Myc, which resulted in cancer cell proliferation and metastasis." (PMID 39215785, 2025). "Our study demonstrates that SIRT6 attenuates energy depletion in WAT and plays a role in the wider context of cancer cachexia." (PMID 39971710, 2025). "In HER2-positive tumors, the overexpression of SIRT6 promotes metastasis and relapse by repressing TBX3 through H3K9ac deacetylation, which confers cancer stem cell–like traits, dormancy, and poor relapse-free survival." (PMID 41463311, 2025). "Conversely, HDAC1, HDAC10, KAT2A, SIRT6, and SIRT7 were upregulated in 13, 16, 17, 14, and 12 cancer types." (PMID 39906742, 2024). "SIRT1 helps cancer cells survive chemotherapy, SIRT2 inhibits cell growth, and SIRT3 controls mitochondrial health, while SIRT4, SIRT5, SIRT6, and SIRT7 each influence metabolism, angiogenesis, and metastasis." (PMID 39682281, 2024). "The deubiquitination of SIRT6 by USP10 and USP48 inhibits cancer formation by preventing the growth and development of cancer cells." (PMID 37175631, 2023). "To date, such molecular pathways are known that regulate the expression and activity of NAMPT in cancers, such as c-MYC/NAMPT/SIRT1, HMGA1/NAMPT/NAD+, FOXO1/NAMPT, NAMPT/miRNA, SIRT6/SIRT1/NAMPT, C/EBPβ/NAMPT." (PMID 37175631, 2023). "Compared with wild-type SIRT6, centSIRT6 more strongly suppressed LINE1 retrotransposons, more efficiently stimulated DNA DSB repair, and more robustly killed cultured cancer cells." (PMID 38016059, 2023). "In malignant BC tissues or cell lines with high levels of RUNX2, endogenous SIRT6 expression is lower, further supporting the role of RUNX2 in suppressing SIRT6 and promoting glycolytic metabolism conducive to cancer progression." (PMID 38203666, 2023). "Also, many studies showed that mutations in NAD+ binding site leads to loss of deacetylase activity of Sirt6 in human cancer cells, human fibroblasts, and 293T cells, indicating that the NAD+ binding site in the Rossmann domain is responsible for the deacetylase activity of Sirt6." (PMID 37497437, 2023). "SIRT6 and SIRT1 enhance the enzymatic NADPH activity by direct deacetylation of the protein, protecting cancer cells from oxidative stress." (PMID 37175631, 2023). "Sirt6 has histone deacetylase (HDAC) activity, and it has key roles in DNA repair, cancer, and progeroid/ageing phenotypes." (PMID 35834102, 2022). "Increased expression of matrix metalloproteases (MMPs) is a characteristic of cancer cells undergoing invasion, and in this study, we found higher levels of MMP9 that have been documented to be regulated by higher SIRT6 status in cancer cells." (PMID 35686673, 2022). "Sirt6, a member of NAD+‐dependent enzymes, is located in mitochondria and plays an important role in regulating ageing, cancer, obesity and cellular energy metabolism." (PMID 35842903, 2022). "In cancer cells the inactivation of SIRT6 leads to the accumulation of nuclear ACLY protein, increases the pool of nuclear acetyl-CoA, and then drives the histone acetylation and cancer invasion." (PMID 39086974, 2022). "SIRT6 and MMP-9 expression in cancer tissues was significantly higher than in paired normal breast tissues." (PMID 35840633, 2022). "Sirtuin 6 (SIRT6) is involved in fatty acid metabolism, influences the secretion of TNF, a cytokine, that plays a key role in cancer pathogenesis, as well as modulates NF-κB-related metabolic pathways." (PMID 36499440, 2022).